CX3CR1 (C-X3-C motif chemokine receptor 1)
Diseases named in the same sentence as CX3CR1 in open-access papers (continued):
Sharing a sentence is not in itself a finding about the gene and the disease.
tumor (continued). "For example, CD123+ pDCs were found to selectively express CCR2, CMKLR1, and CXCR3, receptors known to be involved in DC maturation, trafficking and recruitment at tumor sites whereas XCR1 and CX3CR1, were selectively expressed by CD141+ mDCs and CD1c+ mDCs." (PMID 29795118, 2018). "Chemokine axes, such as fractalkine (CX3CL1)/CX3CR1, C-X-C motif chemokine ligand 12 (CXCL12)/C-X-C chemokine receptor type 4 and 7(CXCR4/CXCR7), CCL2/CCR2, and CCL5/CCR5, are clearly involved in tumor progression." (PMID 30123112, 2018). "Other relevant transcripts that were significantly induced in the tumor CD45+ cells include Bhlhe40, Eomes S1PR1, TIM3 and CX3CR1." (PMID 29423108, 2018). "Since the fractalkine:CX3CR1 pathway has been shown to have a selective bias for cytotoxic lymphocytes such as CD8+ T cells and NK cells, the preferential migration of CD8+ T cells to omentum over tumor might be detrimental for anti-tumor immunity in EAC and other obesity-associated cancers." (PMID 30150990, 2018). "Blockade of CCL26 cognate receptor, CX3CR1, by neutralizing antibody prevented MDSC infiltration and perturbed tumor growth." (PMID 28894087, 2017). "This study demonstrates that ectopic expression of CX3CR1 enhanced the homing of adoptively transferred T cells towards CX3CL1-producing tumors, resulting in increased T cell infiltration in tumor tissues and decreased tumor growth." (PMID 27096098, 2016). "Expression of the inflammatory chemokine receptors, CCR1, CCR2, CCR3, CCR5 and CX3CR1, was significantly enriched on both Foxp3+ and Foxp3− CD4+ T cells within the tumours when compared with spleens and lymph nodes." (PMID 25495686, 2015). "NK cells migrate to lymph nodes mainly by utilizing CXCR3, while their migration to the inflamed tissues including tumor sites involves CCR1, CCR2, CCR5, CXCR3, and CX3CR1." (PMID 24966464, 2014). "TILs express additional chemokine receptor, CX3CR1, and the expression of its ligand, CX3CL1, is elevated in tumor cells in colorectal cancer tissues." (PMID 24966464, 2014). "Another chemokine GPCR, CX3CR1, and its ligand, CX3CL1, recruit TAMs and sustain the survival of TAMs to promote tumor metastasis." (PMID 25110692, 2014). "However, the role of CX3CR1 in the development of the tumor microenvironment remains unclear." (PMID 24245985, 2013). "Using this system we dissected the selective contribution of CX3CR1+CCR2+ cells, which comprise only about 7% of CD11b+ BM cells, to tumor development and angiogenesis." (PMID 22279523, 2012). "The first experiment compared the ability of either BM CD11b+ cells from CCR2+ donors to support tumor development in CCR2−/− mice, and the other experiment compared the ability of purified CX3CR1 (GFP+) cells from CCR2+ mice to do so." (PMID 22279523, 2012). "Flow-cytometric analyses further revealed membrane CX3CR1 expression in both CD45+ and CD45− cells from malignant tumor specimens." (PMID 21750716, 2011). "Dividing these cells into KG+ and KR+ subsets revealed that the increased proportion of GZB+CX3CR1+ cells was most evident within the KR+ population, consistent with reinvigoration of CD8+ T cells present within the tumor at the time of photolabeling (KR+: 34.2% ± 3.5% vs. 18.9% ± 3.7%; P = 0.02)." (PMID 39881590, 2025). "It was speculated in another Mendelian randomization study that CX3CR1 on CD14+ CD16- monocytes may promote the onset of PC through the CX3CR1/CX3CL1 signaling pathway, which is actively involved in promoting tumor angiogenesis, migration, and infiltration." (PMID 40564200, 2025). "Alongside CX3CR1, we also assessed GZB as an effector mechanism mediating tumor-cell lysis." (PMID 39881590, 2025). "Notably, inhibition of CX3CR1 reduced the infiltration of PMN-MDSCs, improved anti-PD-1 therapeutic efficacy, and suppressed tumor growth." (PMID 41280721, 2025). "As expected, neoAg SLP vax initiated on day 7 induced tumor regression in the absence of additional exogenous CX3CR1+CD206+ macrophages." (PMID 39446585, 2024).
tumor (continued). "While early studies have established the pivotal role of Cx3cr1 in macrophage functions, our experiments with older mice expressing Phgdhfl/flCx3cr1-Cre did not reveal any signs of tumor alterations compared to those in Phgdhfl/fl mice." (PMID 38409249, 2024). "For the first time, we also report that a small molecule antagonist of CX3CR1 (KAND567) specifically hindered the transition of monocytes into NLCs in CLL and blocked their survival-promoting effect on CLL cells in vitro, leading to tumor cell apoptosis." (PMID 39594776, 2024). "Furthermore, the expression of anti-tumorigenic genes (ERG2, ERG3, and BTG2) was promoted by the interaction between CX3CR1+ macrophages and NR5A1+ tumor cells through the ligand-receptor INHBA-ACVR1B pair." (PMID 38658971, 2024). "Their findings further showed that the metastasis of CRC cells was lowered when CX3CR1 was absent in the tumor microenvironment." (PMID 38992681, 2024). "Here, we have shown that modulating CX3CR1 with E6130 significantly suppresses NK cell migration towards the soluble chemotactic cues from OAC patient omentum and frees them to traffic towards the tumour in an ex vivo model." (PMID 38369570, 2024). "In the present study, FTY720 treatment eliminated CX3CR1− CD8+ cells in the periphery but not in the tumor." (PMID 38881188, 2024). "Next, we sought to assess the clinical relevance of CX3CR1+ CD8+ TILs and examined whether the presence of this subset in the tumor microenvironment would correlate with the response to ICI therapy." (PMID 38881188, 2024). "As a promising monitor of acute inflammatory response, CX3CR1 expression may have advantages over NLR and PLR in predicting tumor-promotion status, possibility of unfavorable prognosis, and postoperative recurrence." (PMID 38433196, 2024). "It is important to remark that anti-tumor properties have been described for sFKN, while, in some cancers, it has been shown that membrane-bound FKN promotes metastasis of CX3CR1+ cancer cells towards sites with elevated CX3CL1 expression, such as lungs, bones, and others." (PMID 39125578, 2024). "Although our results indicate the differentiation of tumor-specific CD8+ T cells in the tumor, the antitumor reactivity of CX3CR1+ CD8+ T cells remains unclear." (PMID 38881188, 2024). "Previous study observed that CX3CR1 ectopic expression improved the recruitment of adoptively transferred T cells toward CX3CL1-generated cancers, leading to the augmentation of T-cell infiltration and reduction of tumor growth." (PMID 39290304, 2024). "However, the increased expression of CX3CR1 in cancer cells that do not express mFKN and the migration of these cells under the influence of the chemotactic effect of sFKN should be prevented because it promotes tumor growth via angiogenesis and increases the risk of metastasis." (PMID 38731899, 2024). "The expression by tumor-infiltrating NK cells of certain chemokine receptors including CCR2, CCR5, CCR7 and CX3CR1, and the abundance of their respective ligands in the TME has been correlated to enhanced NK cell tumor infiltration and improved cytotoxic response." (PMID 37298470, 2023). "recently confirmed that microglial genes (CX3CR1, TMEM119, and P2RY12) were mainly expressed in the periphery, while activated macrophage genes (TNF, CCL2, LYZ, CCR2, CXCR4, and SIGLEC1) were predominantly detected within the core tumor regions." (PMID 37731483, 2023). "In addition, metalloproteinases MMP3, MMP9, MMP10 and MMP13, known to promote tumor growth, were upregulated by CX3CL1 mediated activation of CX3CR1." (PMID 37771579, 2023). "Except for CXCR6, all cytokines/cytokine receptors were shown to operate in the spine, with CX3CL1, CX3CR1, IL10, CCL2, CXCL12, and CXCR4 mediating bone marrow colonization, CXCL5 and TGFβ promoting tumor cell proliferation, and TGFβ additionally driving bone remodeling." (PMID 36835198, 2023).
tumor (continued). "By reducing these activities, the CX3CR1 monoclonal antibody can disrupt recruitment, facilitate remodeling, and alter the MDSC compartment in the tumor microenvironment, making the combination of CX3CR1 and PD-1 antibody blockade a promising combination therapeutic strategy." (PMID 37771579, 2023). "Additionally, CXCL13+ TH1-like cells (T05) were also enriched in tumor sites, whereas CD4+ANXA1+ TCM (T02) and CX3CR1+ Teff cells (T04 and T09) were mainly detected in blood and ascites." (PMID 37488416, 2023). "A significant increase in tumor foci in the omentum was observed in saline-treated Cx3cr1+/GFP mice (P < 0.0001) but not in saline-treated Cx3cr1GFP/GFP mice." (PMID 37345662, 2023). "Our findings further demonstrated that at least 10% increase of the CX3CR1 score was predictive of response to chemo-immunotherapy with high sensitivity, specificity, PPV, and NPV, compared with pretreatment PD-L1 expression on immune and tumor cells." (PMID 37009132, 2023). "Besides CD4-positive TEMRA cells, GPR56 was also previously identified within a core transcriptome signature of human memory CX3CR1-positive CD8 T cells, and within a gene signature of CD39 and CD103 double-positive tumor-reactive CD8 T cells." (PMID 35804934, 2022). "Regardless of whether clodronate liposomes were administered, we found a large population that consisted of 20–70% CX3CR1+F4/80+ cells, which may indicate some inference by TRMs, and a 5–15% CCR2+F4/80+ population was found in the tumor." (PMID 35326625, 2022). "There were no significant changes among these CCR2- and CX3CR1-expressing populations in the non-tumor peripheral tissues examined." (PMID 36685592, 2022). "We also noted that the tumor enriched C5 cells were characterized by the expression of resting NK cells markers, such as AREG, XCL1, and KLRC1, while the C9 cells, which expressed the CX3CR1 and NKG7, were abundant in normal tissues." (PMID 36008393, 2022). "For instance, one chemokine, i.e., CCL2, might be the prominent driver of CCR2+/CX3CR1+ cell recruitment to the tumor, while the second, i.e., CCL7, is more important for homing to specific niches within tumor." (PMID 36685592, 2022). "Moreover, recent studies revealed that CX3CR1+CD8+T cell subsets not only precisely predicted early response in anti-PD1 therapy, but also enhanced the anti-tumor efficacy in vitro." (PMID 35572515, 2022). "Furthermore, through whole-mount imaging of tumor-immune cell-vascular crosstalk in intact lobes based on liver-CUBIC, we characterized an accumulation of CX3CR1+CCR2+F4/80+ macrophages at metastatic foci in early colorectal liver metastases." (PMID 35910800, 2022). "It has been already demonstrated that Cx3cr1 deletion or replacement with GFP did not affect TAMs infiltration in tumor bearing mice." (PMID 36589283, 2022). "Finally, we sorted the lung tumor-infiltrated MHC-IIhigh and MHC-IIlow TAMs and Ly6C+ inflammatory and CX3CR1+ residential monocytes from 3-week LLC-engrafted mice to evaluate their capacity to boost LLC target cell-specific killing ex vivo." (PMID 35493461, 2022). "Moreover, we ascertained that the different expression of ADRB2, ANGPTL4, BDNF, CBLC, CX3CR1, and IL3RA in tumor and normal group was consistent both in PCR and UALCAN." (PMID 35833114, 2022). "In our study, CD8+ Teff subclusters in peripheral blood, not in tumor/paratumor tissues, highly express CX3CR1 which is related to strong cytotoxic effector function, unique migration pattern and positioning adjacent to the entry site of pathogens." (PMID 35562760, 2022). "However, increased levels of miR-27a-5p were shown to negatively target the expression of CX3CR1 in NK cells in neuroblastoma, consequently reducing the recruitment of CXCR1 to NK cells in the tumor mass." (PMID 36189271, 2022).
tumor (continued). "In addition, tumor-infiltrating Treg cells showed distinct expression of chemokines and chemokine receptors, e.g., IL-8 (CXCL8), CX3CR1, CXCR7, and CCR10, some of which have been proposed as a prognostic marker and/or therapeutic target in cancer." (PMID 33976194, 2021). "In addition, we investigated the relationship between CX3CR1 expression and CRC clinicopathological parameters, including gender, age, tumor location, TNM stage, and tumor size and differentiation." (PMID 35140706, 2021). "They presented that the TCR frequency and clonality of the peripheral CX3CR1-positive CD8+ T cell subset (which included an enriched repertoire of tumor-specific and tumor-infiltrating CD8+ T cells) was increased in tumor-bearing mice who responded to immunotherapy." (PMID 33918147, 2021). "There was a non-significant trend toward increased PB CX3CR1+ CD8+ T cells in B16 tumor-bearing mice without improvement of survival by combined CTLA-4/PD-L1 blockade therapy." (PMID 33658501, 2021). "Furthermore, pre-treatment with a CX3CR1 antagonist can overcome this conditioning by the omental microenvironment and restore NK cell migration towards OAC tumour." (PMID 35008227, 2021). "The levels of Ki-67 expression in the CX3CR1+ CD8+ T cells were significantly higher than in the CX3CR1−(CD27lo CX3CR1− and CD27hi CX3CR1−) subsets 2 weeks after anti-CTLA-4/PD-L1 therapy in CT26 tumor-bearing mice." (PMID 33658501, 2021). "Our data uncover diminished NK cell migration towards OAC tumour tissue conditioned media (TCM) following exposure to omental adipose tissue conditioned media (ACM) and reveal that this migration can be rescued with CX3CR1 antagonist E6130." (PMID 35008227, 2021). "Importantly, using genetically engineered mice, selective deletion of Nhe1 from Cx3cr1+ microglia/myeloid cells elevated CD4+PD-1+ and CD8+PD-1+ tumor infiltration in response to TMZ monotherapy." (PMID 33391535, 2021). "In agreement with this, we found CX3CR1 but not Ki-67 remains elevated in tumor-specific CD8+ T cells during ICI therapy in preclinical models." (PMID 33658501, 2021). "In line with the mRNA results, the protein expression of CX3CR1 was also statistically reduced in the tumor tissues compared with the non-tumor tissues (P < 0.01 or P < 0.001)." (PMID 35140706, 2021). "Tumor cell MVs promote MMP-9 and ERK1/2 phosphorylation in fibroblasts to induce chemoresistance and migration; in turn activated fibroblasts secrete MVs carrying CX3CL1 that more strongly promote migration/invasion of cancer cells expressing CX3CR1." (PMID 32957712, 2020). "Also, adoptive transfer of IL-21-producing CD4+ T cells into tumor-bearing mice induced generation of a CX3CR1+ effector CD8+ T cell pool, leading to improved tumor control." (PMID 33123174, 2020). "Monocytes in the tumor niche differentiate into TAM, which shows CX3CR1 expression." (PMID 32466280, 2020). "Furthermore, ISIM-treated mice contained more circulating CD8+ T cells expressing 4-1BB and CX3CR1, a marker of effector differentiation, and these markers were preferentially expressed in Tet+ CD8+ T cells in 4T1 tumor-bearing mice." (PMID 33110069, 2020). "We observed that p‐S6 baseline levels in Rheb1fl/fl tumours were higher in TAM‐MG than TAM‐BMDM, and these were significantly reduced in TAM‐MG but not in TAM‐BMDM in Cx3cr1‐Rheb1Δ/Δ tumours (Fig EV2A–C)." (PMID 32567735, 2020). "Furthermore, inhibition of CCL-26 by the HIF inhibitor digoxin or through the blockade of CX3CR1 using a neutralizing antibody suppressed MDSC recruitment and tumour growth." (PMID 31835751, 2019). "Proteolytic cleavage of the tumor-suppressive CXCR3 and CX3CR1 chemokines impairs their functions and, on top of this, in feedback loops, the chemokines may even lead to increased expression of the proteases targeting themselves." (PMID 31482487, 2019). "Irradiation and downregulation of CX3CR1 significantly reduced tumor burden at pancreas, while individually both factors did not have any effect." (PMID 29712888, 2018).
tumor (continued). "Furthermore, a recent study has shown that CX3CR1, a receptor for CX3CL1, is exclusively expressed in a subset of CD8+ effector memory T cells infiltrating tumor tissues in patients responding to anti-PD-1 therapy." (PMID 30108590, 2018). "Reduction of CX3CR1 expression leads to reduction in GPR65 and FFAR4 expression, which may affect tumor cell’s ability to uptake FAs, partially explaining reduced omental metastasis." (PMID 29712888, 2018). "Thus, deletion of p16Ink4 and p21Cip1/Waf1 reduces CX3CR1 expression, thereby inhibiting Mo-MDSC accumulation in tumours expressing CX3CL1 and suppressing the tumour progression in mice." (PMID 29234059, 2017). "To confirm the role of reduced CX3CR1 expression in the failure of Mo-MDSC infiltration into tumour allografts, we next assessed whether our findings were reproducible in other syngeneic tumour cell lines." (PMID 29234059, 2017). "On the basis of the findings regarding the chemokine receptor CX3CR1, two killer lectin-like receptor G1 (KLRG1+) mouse NK cell subsets have been defined, and KLRG1+CX3CR1+ NK cells have been found to display impaired IFN-γ production and tumor cell lysis." (PMID 26655673, 2015). "CX3CL1-driven chemotaxis and adhesion are mediated by CX3CR1 that is expressed on different cell types such as NK cells, CD14+ monocytes, cytotoxic effector T cells, B cells, neurons, microglia, smooth muscle cells, and tumor cells." (PMID 24799766, 2014). "Expression of both CX3CL1 and CX3CR1 influences the clinical features and prognosis in patients with HCC since high expression of the chemokine/receptor axis correlates with better prognosis and tumor differentiation." (PMID 24799766, 2014). "MSCs may be recruited into the tumor through FPR2, CCR2, CXCR1, CXCR2, CXCR4, CXCR6, and CX3CR1 depending on the types and locations." (PMID 25110692, 2014). "The biological activities of CX3CL1 are mediated by CX3CR1, that is expressed on different cell types such as NK cells, CD14+ monocytes, cytotoxic effector T cells, B cells, neurons, microglia, smooth muscle cells, and tumor cells." (PMID 24799766, 2014). "Gil-Bernabe and colleagues found that tumor-derived tissue factor (coagulation factor III or CD142) stimulated clot formation and enhanced subsequent tumor cell survival at the metastatic site by recruiting CD11b+/CD68+/F4/80+/CX3CR1+ macrophages." (PMID 25125485, 2014). "Nerve terminations were surrounded by tumor cells with high expression of HIF-1α and CX3CR1." (PMID 22952674, 2012). "In addition, we have identified modulation of the fractalkine receptor CX3CR1 with E6130 and/or remodelling of the tumour chemokine profile with MIP-1α and RANTES as potential therapeutic approaches to limit NK cell migration towards omentum and augment NK cell migration towards OAC tumour." (PMID 38369570, 2024). "Notably, our study does not negate the ability of CX3CR1+ CD8+ T cells to traffic to the tumor microenvironment if tumors secrete CX3CL1." (PMID 38881188, 2024). "Although, CX3CR1 was not correlation with tumor purity (r = −0.29, P = 9.27e−11)." (PMID 38241595, 2024). "Taken together, our results from the HuPD-H1 model show that expansion of the CX3CR1+CD8+ T cell subset can be induced by the presence of ICB therapy at the time of T cell priming, and an increase in these cells is correlated with enhanced tumor rejection in the anti–PD-1/L1-treated mice." (PMID 36656137, 2023). "In agreement with our hypothesis, the pharmacological inhibition of CX3CR1 by the administration of the allosteric noncompetitive FKN antagonist AZD8797 accelerated tumor progression (P < 0.05)." (PMID 37366231, 2023). "The sequence analysis also demonstrated that helped CD8+ T cells gained a stronger extravasation potential by upregulation of chemokine receptors CXCR4 and CX3CR1,151 which could bind to CXCL12 and CX3CL1 from tumor cells, thus inducing CTLs infiltration into TME to exert antitumor effects." (PMID 37829505, 2023).